E2F5 (E2F transcription factor 5)
Description:
Transcriptional activator that binds to E2F sites, these sites are present in the promoter of many genes whose products are involved in cell proliferation. May mediate growth factor-initiated signal transduction. It is likely involved in the early responses of resting cells to growth factor stimulation. Specifically required for multiciliate cell differentiation: together with MCIDAS and E2F5, binds and activate genes required for centriole biogenesis.
Synonyms: E2F-5
Tractability: PROTAC: ubiquitination databases record sites on it. Other modalities: a drug acting on it is in phase 2 or 3 trials.
Gene: Protein-coding gene on chromosome 8 (85,177,154 to 85,217,158, forward strand). Ensembl gene ENSG00000133740.
Subcellular location: Nucleus
Subcellular location (Human Protein Atlas): Nucleoplasm; Nucleoli; Vesicles
Pathways (Reactome):
Cell Cycle: Cyclin A:Cdk2-associated events at S phase entry; Cyclin D associated events in G1; Cyclin E associated events during G1/S transition; G0 and Early G1; G1/S-Specific Transcription; Transcription of E2F targets under negative control by DREAM complex; Transcription of E2F targets under negative control by p107 (RBL1) and p130 (RBL2) in complex with HDAC1
Signal Transduction: SMAD2/SMAD3:SMAD4 heterotrimer regulates transcription
Gene Ontology:
Molecular function: DNA-binding transcription activator activity; DNA-binding transcription activator activity, RNA polymerase II-specific; protein binding; DNA-binding transcription factor activity; DNA-binding transcription factor activity, RNA polymerase II-specific; RNA polymerase II cis-regulatory region sequence-specific DNA binding; protein dimerization activity
Biological process: negative regulation of DNA-templated transcription; regulation of DNA-templated transcription; regulation of transcription by RNA polymerase II; positive regulation of DNA-templated transcription; positive regulation of transcription by RNA polymerase II
Cellular component: nucleoplasm; chromatin; DRM complex; nucleus; RNA polymerase II transcription regulator complex; cytoplasm; transcription regulator complex
Genetic constraint (gnomAD): Loss-of-function variants: 15 observed, 22.9 expected, observed/expected ratio (o/e) 0.65, 90% interval 0.44 to 1.01. The upper end of that interval is the gene's LOEUF score, 1.01, which puts it in group 4 of 6, group 1 being the genes least tolerant of losing a copy. Missense variants: 236 observed, 255.83 expected, observed/expected ratio (o/e) 0.92, 90% interval 0.83 to 1.03. Synonymous variants: 88 observed, 94.09 expected, observed/expected ratio (o/e) 0.94, 90% interval 0.79 to 1.12.
Homologues: Orthologues: chimpanzee E2F5 (99% identical), macaque E2F5 (98% identical), pig E2F5 (94% identical), dog E2F5 (94% identical), rat E2f5 (88% identical), mouse E2f5 (87% identical), tropical clawed frog e2f5 (69% identical), zebrafish e2f5 (57% identical), Caenorhabditis elegans efl-3 (25% identical). Paralogues in human: E2F4 (61% identical), E2F2 (32% identical), E2F1 (29% identical), E2F3 (29% identical), E2F7 (24% identical), E2F8 (23% identical), E2F6 (22% identical).
Diseases named in the same sentence as E2F5 in open-access papers:
E2F5 is named in the same sentence as 61 diseases in open-access papers, as found by Europe PMC text mining. Sharing a sentence is not in itself a finding about the gene and the disease. The quoted sentences say what the papers report.
ovarian carcinoma (16 papers, 2007 to 2024). A malignant neoplasm originating from the surface ovarian epithelium. "Previous studies demonstrate that aberrant expression of E2F5 is associated with the malignancy of ovarian cancer, gastric cancer, lung cancer, and hepatocellular carcinoma." (PMID 38271139, 2024). "The E2F5 status significantly improves the diagnostic accuracy in epithelial ovarian cancer (OEC), and the presence of CA125 or E2F5 increases the sensitivity of OEC detection to 97.9% and the specificity to 72.5%." (PMID 34476219, 2021). "Many studies have shown that E2F5 is a oncogene in cancer development, such as breast cancer, ovarian cancer, hepatocellular carcinoma, esophageal squamous cell carcinoma and prostate cancer." (PMID 33390186, 2021). "In ovarian cancer cells, miR-132 suppresses the cell proliferation, invasion, migration by targeting E2F5." (PMID 31906769, 2020). "The transcriptional levels of E2F5 in ovarian carcinoma (fold change = 4.355 and p–value = 2.71E-08) were significantly different from those in the normal samples in Yoshihara's dataset." (PMID 30967995, 2019). "E2F5, an important member of the E2F family, is a potential oncogene in breast cancer, ovarian cancer, HCC, esophageal squamous cell carcinoma, prostate cancer, and colorectal cancer." (PMID 27259277, 2016). "It was found that interferon-gamma treatment for ovarian cancer caused a reduction of the proliferation-promoting TFs E2F1 and E2F2, at the same time it also increased the inhibiting TFs E2F4 and E2F5." (PMID 20181230, 2010). "Moreover, this miRNA directly targets E2F5, a key player in DNA synthesis, negatively regulating the mTOR signaling pathway and hindering the development of ovarian cancer cells." (PMID 38793064, 2024). "Furthermore, it was reported that MALAT1 sponges miR-1271-5p and facilitates multiple myeloma and ovarian cancer progression by regulating SOX13 and E2F5, respectively." (PMID 35320950, 2022).
breast carcinoma (15 papers, 2014 to 2024). "An increased gene copy number of E2F5 is detected in two independent cohorts of patients with breast cancer, and there is a positive association of E2F5 amplification with a pathological basal phenotype and a worse clinical outcome." (PMID 33390186, 2021). "In our study, we identified two different alternatively-activated TGF-β signaling pathways, and the E2F5-related sub-pathway is related to breast cancer, while the E2F4 related one is a risk for metastasis and potential worse survival." (PMID 31557971, 2019). "SNHG16 has been introduced to assist cell migration in breast cancer by sponging miR-98 to regulate E2F5." (PMID 34991683, 2022). "In breast cancer tissues, E2F5 was identified as a target of miR-154 with the inversely correlated expression." (PMID 34944712, 2021). "For example, SNHG16 competes with E2F5 to bind with miR-98, thus promoting breast cancer cell migration." (PMID 32242897, 2020). "E2F5 was significantly active in primary breast cancer, and E2F4 was significantly active in the metastasis." (PMID 31557971, 2019). "Overexpression of SNHG16 could promote the migration of breast cancer cells through modulating miR-98/E2F5 axis." (PMID 31781497, 2019). "Moreover, they found that SNHG16 significantly promoted breast cancer cell migration by competitively binding miR-98 with E2F5." (PMID 30962265, 2019). "Except for known disease proteins of breast cancer that found in the 6 protein complexes, many disease proteins that were associated with many other types of diseases could be found, with examples including E2F4, E2F5, HRAS, JUN, FOS." (PMID 24565064, 2014). "The long noncoding RNA SNHG16 promoted breast cancer cell migration by acting as a competitive endogenous RNA (ceRNA) for E2F5 by binding with miR-98, while the miR-98-5p/IGF2 axis affected herceptin sensitivity in HER2 positive breast cancer." (PMID 38872210, 2024). "Conversely, overexpression of either E2F4 or E2F6, as well as E2F5 which also forms a DREAM complex, was able to repress A3B expression to varying extents in multiple different breast cancer cell lines." (PMID 32985974, 2020). "Other notable genes decreased by SK1 KD were NDUFA2 in prostate and E2F5, NAGK, VAPB, NFATC3, CDK2 in breast cancer cell lines." (PMID 30971929, 2019). "In the calcium signaling and TGF beta signaling pathways, node E2F5 and E2F4 were significantly active in primary breast cancer and metastasis, respectively." (PMID 31557971, 2019).
prostate carcinoma (14 papers, 2014 to 2024). A carcinoma that arises from epithelial cells of the prostate gland. "Research indicates that the dysregulation of the E2F5/p38/SMAD3 axis is associated with uncontrolled cell proliferation in prostate cancer (PCa)." (PMID 39085482, 2024). "Recent studies have shown that E2F5 expression was associated with several tumours, such as glioblastoma, prostate cancer and Rb." (PMID 30487158, 2018). "Upregulated E2F5 is associated with the positive regulation of TGF-β signaling in prostate cancer, which might also occur in CRC." (PMID 38132443, 2023). "The copy number gain of genes in chromosomal region 8q21-24 has been demonstrated to be associated with genesis and progression of prostate cancer (PCa) with a significant amplification of E2F5 and MYC genes, the former being included among our G3 up/amplified genes." (PMID 24866763, 2014). "Given that prostate cancer is a highly heterogeneous tumor, somatic mutations of clinicopathologically significant E2Fs, including the E2F1, E2F2, E2F3, E2F5, and E2F6, were further investigated in PCa patients." (PMID 35531101, 2022). "As a transcription factor, E2F3 directly targets IL-6 signaling and is involved in prostate tumorigenesis, and dysregulation of the E2F5/p38/SMAD3 circuitry has been found to reinforce the protumorigenic switch of TGFβ signaling in prostate cancer." (PMID 35531101, 2022). "Overall, E2F1, E2F2, E2F3, and E2F5 were found to be correlated with the malignant progression of prostate cancer." (PMID 35531101, 2022). "Down-regulation of E2F5 by miR-1-3p can lead to the inhibition of prostate cancer cell aggressiveness in vitro." (PMID 35531101, 2022). "In a study of prostate cancer, miR-1-3p showed downregulation, and its ectopic expression suppressed cell growth and cell cycle progression in vitro and in vivo through targeting of 3′-UTRs of two key cell cycle genes, E2F5 and PFTK1." (PMID 35864552, 2022). "For example, E2F5 was upregulated in prostate cancer and could accelerate cancer migration and invasion." (PMID 34784267, 2022). "E2F5 is found highly expressed in several tumors, such as glioblastoma, and prostate cancer." (PMID 29754146, 2018). "Subsequently, we further investigated the alteration of immune cell components in samples with altered expressions of E2F1, E2F2, E2F3, E2F5, and E2F6 in prostate cancer based on TCGA." (PMID 35531101, 2022). "In summary, E2F1, E2F2, E2F3, E2F5, and E2F6 were found to be correlated with the malignant progression of prostate cancer." (PMID 35531101, 2022). "Our results showed that the expression of E2F1–3, E2F5, and E2F6 was higher in prostate cancer tissues than in benign tissues." (PMID 35531101, 2022). "Our recent study found that miR-212-5p/miR-449a inhibits the expression of E2F5 and mediates circCDK13/CDK13 feedback regulation to promote the occurrence and development of prostate cancer." (PMID 34692488, 2021). "It has been observed that E2F transcription factor 5 (E2F5) and/or PFTAIRE Protein Kinase 1 (PFTK1, also known as CDK14) are upregulated in various types of human cancers, including prostate cancer." (PMID 30185212, 2018). "Consequently, E2F1, E2F4, and E2F5 had negative correlations with DBNDD1 expression in normal prostate tissues but positive correlations in prostate carcinoma tissues." (PMID 37569304, 2023).
hepatocellular carcinoma (11 papers, 2007 to 2024). A malignant tumor that arises from hepatocytes. "FOXN3 possesses a unique forkhead box region that can interact with the promoter of the E2F5 transcription factor, inhibiting hepatocellular cancer cell proliferation by downregulating E2F5 mRNA and protein expression." (PMID 36324573, 2022). "In the TGF-β signaling pathway, E2F5 status was reported to improve the diagnosis of the malignancy of breast tumors, epithelial ovarian cancer, and hepatocellular carcinoma." (PMID 31557971, 2019). "Our study demonstrated that HBV could promote hepatoma cell proliferation by down-regulating E2F5 expression." (PMID 24529171, 2014).
glioblastoma (10 papers, 2018 to 2023). The most malignant astrocytic tumor (WHO grade IV). "In the Sun Brain Statistics, E2F5 was also overexpressed in anaplastic astrocytoma with a fold change of 2.545, in oligodendroglioma with a fold change of 2.580, and in glioblastoma with a fold change of 2.877." (PMID 33381564, 2020). "In the Murat Brain Statistics, E2F5 was also overexpressed in glioblastoma with a fold change of 2.016." (PMID 33381564, 2020). "Furthermore, E2F5 was highly expressed in glioblastoma tumors, and it has been reported that miR-Let-7c and miR-129-3p inhibited glioma development by targeting E2F5." (PMID 36979479, 2023). "miRNA-129-3p suppressed growth of glioblastoma via targeting E2F5." (PMID 33381564, 2020). "MiR-1179 by targeting E2F5 could inhibit glioblastoma cell proliferation and cell induce G0/G1 arrest." (PMID 33330110, 2020). "E2F5 was highly expressed in all kinds of tumors, such as prostate tumor and glioblastoma." (PMID 33381564, 2020). "Remarkably, E2F5 was significantly correlated with M1 macrophage markers (IRF5) and monocyte markers (CD115), suggesting that it plays a role in regulating monocyte polarization in glioblastoma." (PMID 36979479, 2023). "Compared with LGG, except for E2F3 and E2F5, all E2Fs were highly expressed in HGG samples and correlated with grade progression, with highest expression attributed to glioblastoma (GBM, grade IV)." (PMID 32064771, 2020).
colorectal cancer (9 papers, 2010 to 2021). A primary or metastatic malignant neoplasm that affects the colon or rectum. "In colorectal cancer, the shRNA inhibition of SNHG6 causes increased level of miR-181a-5p and decreased level of E2F5 (E2F transcription factor 5), a transcription factor, which further decreases the number of colonies and invasive cells, as well as cell cycle arrest during in vitro studies." (PMID 32318335, 2020). "Two mRNAs (E2F5 and CDC16) that were associated with altered colorectal cancer survival were associated with six of the miRNAs associated with altered colorectal cancer survival: hsa-miR-15a-5p, hsa-miR-17-5p, hsa-miR-19b-3p, hsa-miR-20a-5p, hsa-miR-20b-5p, and hsa-miR-92a-3p." (PMID 29725503, 2018). "DNA amplifications for E2F5 (8p22-q21.3) has been observed during sporadic colorectal cancers." (PMID 20181230, 2010). "Likewise, hsa-circ-001569 may promote the proliferation and invasion of colorectal cancer cells by sponging miR-145 and subsequently upregulating the expression of E2F5, BAG4, and FMNL2." (PMID 31821171, 2019). "However, as activators have shown repressive activity and repressors have shown activating effects, it may be that, as we see positive beta coefficients in these interactions, E2F5 acts as a transcriptional enhancer of these miRNA clusters in colorectal cancer." (PMID 29725503, 2018). "Some researchers provide evidences that circ_001569 acts mechanically as a miRNA sponge to inhibit miR-145 activity, and subsequently up-regulates miR-145 targets E2F5, BAG4 and FMNL2 to promote cell proliferation and invasion in CRC (colorectal cancer)." (PMID 28279183, 2017). "For example, circ_005169 exerted oncogenic function via sponging miR-145 and increasing the expression of E2F5, BAG4, and FMNL2 in colorectal cancer cells." (PMID 28219405, 2017).
glioma (7 papers, 2019 to 2023). A benign or malignant brain and spinal cord tumor that arises from glial cells (astrocytes, oligodendrocytes, ependymal cells). "Let-7c downregulated the expression of E2F5 which blocks cell growth, invasion, proliferation, and migration in glioma cells." (PMID 34947956, 2021). "Moreover, Let-7c inhibited glioma development by targeting E2F5." (PMID 33381564, 2020). "We observed that TWEAK treatment increased nuclear E2F4 and E2F5 protein levels in glioma cells, with E2F4 having greater nuclear translocation in BT25 cells and E2F5 in BT114 cells." (PMID 36945490, 2023). "E2F5, E2F7, and E2F8 were significantly upregulated in brain and CNS cancers relative to normal brain samples, while E2F1 and E2F3 were more highly expressed in normal brain samples in the ONCOMINE dataset." (PMID 34617871, 2021). "Furthermore, we demonstrate that the E2F transcription factors E2F4 and E2F5 directly regulate NIK transcription and are required to promote glioma cell invasion in response to TWEAK." (PMID 36945490, 2023). "Finally, due to their role in promoting the cell cycle of gliomas, NFAT5 and E2F5 TFs are downregulated in seven days for the D-GSC#83 and D-GSC#1 lines, respectively." (PMID 34440820, 2021).
lung carcinoma (7 papers, 2010 to 2024). "In human lung carcinoma E2F5 expression was reportedly increased and was significantly associated with worse OS." (PMID 30487158, 2018). "Hsa-miR-372 is already a potential marker of lung cancer, and regulates an ATPase family member ATAD2, a translocase of inner mitochondrial membrane 17 (TIMM17A) and the transcription factor E2F5." (PMID 24866763, 2014).